CDX2 (caudal type homeobox 2)
Diseases named in the same sentence as CDX2 in open-access papers (continued):
Sharing a sentence is not in itself a finding about the gene and the disease.
gastric cancer (continued). "At present, there is no specific tumor marker for gastric cancer; however, CA199, CK-7, and CDX-2 are commonly used as markers of gastrointestinal tumors." (PMID 32337226, 2020). "The tissue of this patient showed typical immunological markers of gastric cancer, that was, CEA, CK7 and CD20 were all positive, while CDX2 was negative." (PMID 33060715, 2020). "ZJU-0430 original gastric cancer tissues positively expressed most gastrointestinal tract markers (CK20, CAD17, and CDX2), and negative expressed β-catenin and SATB2." (PMID 31367188, 2019). "Based on the RNA‐sequencing data of patients with stage II/III gastric cancer from the public ACRG cohort, there were 39 genes upregulated and 194 genes downregulated in the CDX2‐negative subgroup when compared with the CDX2‐positive subgroup (p < 0.05, false discovery rate <0.25)." (PMID 37602699, 2023). "We conducted overexpression experiments with gastric cancer cell lines and found that HOXA13 could upregulate CDX2 in SGC-7901 cells but not in MKN-28 cells." (PMID 35999201, 2022). "In addition, the original GBC tumour showed negatively staining CDX2, and the original gastric cancer showed positive staining for CK20, CAD17, CDX2, and was negative for β-catenin and SATB2." (PMID 31367188, 2019). "A significant association was observed between oct-1 and cdx2 expression in the gastric carcinoma cell lines, GP220 and MKN45; however, whilst oct-1 was shown to bind to the cdx2 promoter, a direct effect of oct-1 in the transactivation of cdx2 was not demonstrated." (PMID 19412438, 2007). "In addition, gastric cancers with CDX2 induction and a parallel induction of HNF4A displayed a higher rate of CIN (83% of cases) compared with all cancers with CDX2 induction (CIN in 63.3% of cases) or the cohort with no CDX2 induction (CIN in 43.1% of cases)." (PMID 39768557, 2024).
breast carcinoma (48 papers, 2008 to 2025). "Initially, we found that CDX2, which was frequently studied in intestinal cancer, was associated with the survival of patients with breast cancer." (PMID 31938021, 2020). "Further, haplotype analyses suggested that the specific combinations of alleles inferred from the ApaI, TaqI, FokI, BsmI and Cdx2 were associated with visceral adiposity changes in breast cancer survivors treated with vitamin D3." (PMID 31395070, 2019). "The analysis of Cdx2 polymorphism across our panel of breast cancer cell lines evidenced the presence of different Cdx2 genotypes: AG in MDA-MB-231, SUM 159PT, MCF7 and T-47D, GG in HCC1143, BT20 and HCC1954 and AA in SK-BR-3, BT549 MDA-MB-468." (PMID 25849303, 2015). "For this reason, and driven by our results on the cell lines, we performed additional experiments among Cdx2 polymorphism and estrogen receptor ER expression in different breast cancer subtypes." (PMID 25849303, 2015). "In summary, our clinical findings revealed a close association between specific VDR Cdx2 polymorphism and breast cancer bearing more aggressive phenotype." (PMID 25849303, 2015). "The CDx2 AG genotype has been reported to decrease breast cancer risk, whereas the AA genotype increases this risk." (PMID 25799416, 2015). "The FtCA haplotype (versus the FTCG reference haplotype) contains the transcriptionally more active Cdx2 A allele, which is expected to be associated with a decreased risk for breast cancer." (PMID 18419802, 2008). "In a haplotype analysis, we found the haplotype FtCA (FokI F, TaqI t, VDR-5132 C, Cdx2 A) to be associated with a significantly greater breast cancer risk as compared with the most frequent haplotype (FTCG)." (PMID 18419802, 2008). "We therefore assessed the association of FokI, TaqI, VDR-5132 and Cdx2 SNPs and their associated haplotypes with postmenopausal breast cancer risk and possible effect modification by serum 25(OH)D in this study population." (PMID 18419802, 2008). "In a haplotype analysis the haplotype FtCA (FokI F, TaqI t, VDR-5132 C, Cdx2 A) was associated with a significantly higher breast cancer risk as compared with the most frequent haplotype (FTCG)." (PMID 18419802, 2008). "The GG genotype of Cdx2-VDR gene polymorphism may increase the risk of developing breast cancer in young female patients in South Pakistan." (PMID 25799416, 2015). "However, the published data examining the relationship between VDR Cdx2 variants and breast cancer susceptibility have been contradictory." (PMID 25799416, 2015). "Cdx2 VDR polymorphism can play an important role in breast cancer, modulating the activity of VDR." (PMID 25849303, 2015). "Haplotype analysis revealed the haplotype FtCA (FokI F, TaqI t, VDR-5132 C, Cdx2 A), which contains the TaqI t allele, to be associated with a significantly greater breast cancer risk as compared with the most frequent haplotype FTCG (OR = 1.43, 95% CI = 1.00 to 2.05)." (PMID 18419802, 2008). "However, under the log-additive model, the haplotype FtCA (FokI F, TaqI t, VDR-5132 C and Cdx2 A) was significantly associated with breast cancer risk compared with the most common haplotype FTCG (OR = 1.43, 95% CI = 1.00 to 2.05)." (PMID 18419802, 2008). "The G allele of Cdx2 was associated with lower risk of breast cancer in AA women in our study and this finding was in contrast to the speculated functional alteration that the variant G allele resulted in lower binding of the Cdx2 protein and thus lower transcriptional activity of VDR." (PMID 22480149, 2012). "The characteristic immunophenotypic profile of CK7+/CK20- combined with GATA3+/CDX2- or GATA3+/SATB2- patterns provides definitive evidence supporting metastatic breast carcinoma to gastrointestinal sites." (PMID 40313249, 2025). "For example, TTF-1 and CDX2 can also show positive rates of 4.6% and 1.8% in breast cancer respectively." (PMID 40822238, 2025).
breast carcinoma (continued). "A comprehensive panel comprising ER, PR, GCDFP-15, CK7, CK20, and CDX2 proves optimal in detecting gastric metastases originating from breast cancer." (PMID 39399168, 2024). "CAF‐derived exosomes were able to enhance breast cancer cell proliferation and to induce the epithelial‐mesenchymal transition via the regulation of the CDX2/HOXA5 pathway." (PMID 35857905, 2022). "In colorectal and breast cancers, Cdx2 is known as a tumor suppressor that antagonizes cancer metastasis by inhibiting cell migration." (PMID 36051443, 2022). "Over-expression of CDX2, a transcriptional factor called caudal type homeobox 2 in MCF7 breast cancer cells alleviates tumor growth and micro-metastasis by up-regulating let-7b and inhibiting COL11A1 expression." (PMID 34572067, 2021). "In xenograft mouse models of breast cancer, COL11A1 expression is negatively regulated by transcription factor CDX2 and microRNA let-7b and the loss of COL11A1 expression by upregulating CDX2 let-7b suppressed metastasis." (PMID 33668097, 2021). "This miRNA packed in exosomes secreted by cancer associated fibroblasts enhances the epithelial–mesenchymal transition (EMT) and aggressiveness of breast cancer by targeting caudal-related homeobox 2 (CDX2)." (PMID 33807023, 2021). "Western blot analysis demonstrated that the CDX2 protein was poorly expressed in breast cancer tissues." (PMID 31938021, 2020). "Our findings further indicated that CDX2 was poorly expressed in breast cancer, while the over-expressed CDX2 diminished the migration and invasion abilities of breast cancer epithelial cells." (PMID 31938021, 2020). "Overall, the current study verified the CDX2/let-7b/COL11A1 modulation in breast cancer epithelial cells, and investigated the tumor growth and metastasis through in vivo models." (PMID 31938021, 2020). "In the present study, we first predicted the targeting relationship between CDX2 and let-7b using the TargetScan website with breast cancer microarray data, and examined the binding of CDX2 to the let-7b promoter region with ChIP assay." (PMID 31938021, 2020). "As compared to adjacent normal tissues, CDX2 expression was decreased in breast cancer tissues, and the CDX2 protein was located at the nucleus and stained in brown (p < 0.05)." (PMID 31938021, 2020). "Recently, a study documented reduced CDX2 expression in breast cancer, while its methylation level is elevated." (PMID 31938021, 2020). "With our research, our endeavor is to explore the role of the CDX2/let-7b/COL11A1 axis in breast cancer cell activities." (PMID 31938021, 2020). "The objective of this study is to assess the relationship between the Cdx2 VDR polymorphism and the activities of VDR in human breast cancer cell lines and carcinomas breast patients." (PMID 25849303, 2015). "In particular, ER(-) breast cancer cells with Cdx2 genotype AA are more responsible to vitamin D compared to cells with genotype AG/GG." (PMID 25849303, 2015). "The concept map analysis using Oncomine revealed that CDX2 as one of the top 1% of the underexpressed gene in all but one breast cancer datasets." (PMID 23982413, 2013). "In terms of immunohistochemical surveys, ER and GATA3 positivity and caudal type homeobox 2 (CDX2) negativity may support the diagnosis of gastrointestinal metastases from breast cancer." (PMID 37845365, 2023). "Wang reported that CDX2 overexpression could alleviate breast cancer progression by upregulating microRNA let-7b and inhibiting COL11A1 expression." (PMID 36160004, 2022). "Moreover, up‐regulation of CDX2 contributes to the suppression of proliferation and elevation of apoptosis of breast cancer epithelial cells." (PMID 33621425, 2021). "CDX2 and let-7b were poorly expressed in breast cancer cells and tissues." (PMID 31938021, 2020). "Similarly, we uncovered that CDX2 inhibited the migration and invasion of breast cancer epithelial cells by up-regulating let-7b." (PMID 31938021, 2020).
breast carcinoma (continued). "On the basis of existing literature data, we carried out studies in an effort to investigate the possible CDX2 may act as a significant cytokine in breast cancer." (PMID 31938021, 2020). "In the current study, we proposed that breast cancer metastasis was correlated with CDX2, and CDX2 could inhibit breast cancer progression by up-regulating let-7b." (PMID 31938021, 2020). "In conclusion, our results indicate that changes in inflammatory biomarkers (plasma MMP9 and TNFα) associated with breast cancer risk and survival in breast cancer survivors with low plasma 25(OH)D levels, supplemented with vitamin D3 depends on VDR SNPs (Cdx2, TaqI and BsmI) and haplotypes." (PMID 31167402, 2019). "A non-significant association was observed between VDR cdx2 polymorphism and breast cancer, however the GG genotype was at risk (OR = 1.832, 95% CI = 0.695–4.828) of developing breast cancer." (PMID 25799416, 2015). "In the present study, we investigated the Cdx2 polymorphism in the vdr gene in a large spectrum of ER-positive (MCF7 and T-47D) and ER-negative (MDA-MB-231, SUM 159PT, SK-BR-3, BT549, MDA-MB-468, HCC1143, BT20 and HCC1954) human breast cancer cell lines." (PMID 25849303, 2015). "The frequency of the A allele is 74% in Africans, 43% in Asians and 19% in Caucasians.The A allele allows the Cdx2 transcription factor to bind more effectively, thereby increasing VDR transcriptional activity thus decreasing the breast cancer incidence, whereas the G allele has the opposite effect." (PMID 25799416, 2015). "Based on these observations, we hypothesized that vitamin D might differently affect the migratory capability of ER(–) breast cancer lines according to Cdx2 status." (PMID 25849303, 2015). "In conclusion, our data on cultured cells suggest that VDR Cdx2 status could be a marker for the use of vitamin D in the treatment on ER(–) breast cancer histotype." (PMID 25849303, 2015). "Moreover, in vitro observations established a different breast cancer cell sensitivity to vitamin D treatment on the base of their VDR Cdx2 status." (PMID 25849303, 2015). "Furthermore, the potential relationship among Cdx2 VDR polymorphism and a number of biomarkers used in clinical management of breast cancer was assessed in an ad hoc set of breast cancer cases." (PMID 25849303, 2015). "SOX2/CDX2 ratio had prognostic relevance in CSC-enriched breast cancers." (PMID 23982413, 2013). "Since SOX2 and CDX2 have been shown to repress each other's expression, we next asked whether ratio between two genes has an impact on breast cancer outcome." (PMID 23982413, 2013). "We further confirmed specificity of our findings to the colonic claudin-1 expression as similar transient overexpression of Cdx1, Cdx2 or GATA4 in human breast cancer cells (MCF-7) or renal epithelial cells (MDCK II cells) did not increase claudin-1 promoter activity." (PMID 22719836, 2012). "In AA women, four SNPs in VDR - rs12721364, rs2239186, rs886441, and rs11568820 (Cdx2) - but none in CYP24A1 were associated with breast cancer risk at a nominal significance level of 0.05." (PMID 22480149, 2012). "Furthermore, the expression of CDX2 was diminished in human breast cancer epithelial cell lines MCF-7 and MDA-MB-231 compared to that of normal human breast epithelial cell line HBL-100, where the MCF-7 cell line exhibited the lowest expression of CDX2 (p < 0.05)." (PMID 31938021, 2020). "Therefore, it would be reasonable to suggest that poor expression of CDX2 is correlated with migration and invasion of breast cancer epithelial cells, and could be countered by over-expression of CDX2." (PMID 31938021, 2020). "Cdx2 VDR polymorphism and antiproliferative effects of vitamin D treatment were investigated in a panel of estrogen receptor-positive (MCF7 and T-47D) and estrogen receptor-negative (MDA-MB-231, SUM 159PT, SK-BR-3, BT549, MDA-MB-468, HCC1143, BT20 and HCC1954) human breast cancer cell lines." (PMID 25849303, 2015).
breast carcinoma (continued). "Our results may suggest a potential effect of Cdx2 VDR polymorphism on the efficacy of vitamin D treatment in aggressive breast cancer cells (estrogen receptor negative)." (PMID 25849303, 2015). "We investigated the Cdx2 status in 2 ER-positive (MCF7 and T-47D) and in 8 ER-negative (MDA-MB-231, SUM 159PT, SK-BR-3, BT549, MDA-MB-468, HCC1143, BT20 and HCC1954) human breast cancer cell lines by pyrosequencing analysis." (PMID 25849303, 2015). "In agreement with other reported papers, SKBR3, MDA-MB-468 and BT549, characterized by AA Cdx2 status, showed a higher level of VDR in comparison to the other 5 ER(–) breast cancer cell lines." (PMID 25849303, 2015). "ATRA reduced mammosphere-forming ability of a subset of breast cancer cells, which correlated with induction of apoptosis, reduced expression of SOX2 but elevated expression of its antagonist CDX2." (PMID 23982413, 2013). "miR-181d-5p contained in CAF-derived EVs in breast cancer promotes proliferation, invasion, migration, and EMT and inhibits apoptosis of cancer cells by targeting caudal-related homeobox 2 (CDX2) and downregulating CDX2 and their downstream gene homeoboxA5 (HOXA5)." (PMID 36674900, 2023). "There is no proven relation between Cdx2, Bgl1, Taq1 and breast cancer (however, some studies have proven a putative connection with Cdx2)." (PMID 34638264, 2021). "TransmiR database and the relevant microarray of breast cancer, GSE45666 indicated that CDX2 may mediate the let-7b." (PMID 31938021, 2020). "Human breast cancer epithelial cell line MCF-7 was treated with over-expressed CDX2, let-7b mimic, shRNA against COL11A1 and their negative controls." (PMID 31938021, 2020). "These tests can be completed with CDX2 and CK19 for upper gastrointestinal tract, biliary ducts and pancreas, thyroglobulin for thyroid adenocarcinoma, NY-BR-1 and GATA-3 for female breast cancer, Mel-A, S100 and HMB45 for melanoma, and vimentin and Mel-A for kidney and adrenal gland tumors." (PMID 29116378, 2018). "The linkage disequilibrium (LD) pattern between the Cdx2 and other VDR polymorphisms has not been studied with respect to breast cancer risk." (PMID 25799416, 2015). "Undeniably, adequate research has not been performed to determine the potential link between Cdx2 and breast cancer development in Pakistan." (PMID 25799416, 2015). "In this analysis, we used organ-specific antibodies, including TTF-1 for lung cancer, WT-1 or PAX8 for gynecological cancers, mammaglobin or GCDFP-15 for breast cancer, PSA for prostate cancer, CDX2 for gastrointestinal cancers, and uroplakin for urothelial cancers." (PMID 22299055, 2012). "Besides, in breast cancer, CAFs exosomal miR-181d-5p facilitated EMT by regulating CDX2/HOXA5." (PMID 36319622, 2022). "In breast cancer, CAFs-derived exosomes carrying miR-181d-5p can promote proliferation, invasion, migration, and EMT and inhibit apoptosis of cancer cells by targeting caudal-related homeobox 2 (CDX2) and then downregulating CDX2 and its downstream gene -homeobox A5 (HOXA5)." (PMID 34852849, 2021). "Moreover, CDx2 was the most significant predictive biomarker of poor survival, thus highlighting the clinical significance of FOXC2 as a CDx2 repressor that might be relevant to basal-like breast cancer." (PMID 40764669, 2025). "While markers usually positive in gastric adenocarcinoma such as cytokeratin 20, CDX2, MUC5AC, and Hep Par 1 were negative, those supporting breast carcinoma (estrogen and progesterone receptors, cytokeratin 7, and GATA3) decorated the cancer cells." (PMID 25400965, 2014). "Metastasis to a lymph node in the axillary region occurred, but the positive reaction for CDX2 and the negative reaction for CK7 indicated that the metastatic foci were from rectal cancer and not from unknown breast cancer." (PMID 33388078, 2021). "Metastatic breast carcinomas are often positive for CK7, ER and PR, but negative for CK20 and CDX2." (PMID 23181599, 2012).
breast carcinoma (continued). "Further, our finding that similar overexpression of Cdx1, Cdx2 or GATA4 in the renal epithelial and breast cancer cells had no apparent effect upon claudin-1 expression suggest that this is not a universal mechanism of claudin-1 expression and is rather colon specific." (PMID 22719836, 2012). "Pretreatment CDX2 pCTCs can be detected in none of the patients with BCD (colitis, haemorrhoids, colorectal ulcers and hyperplastic polyps) and 2.5% (2 out of 80) patients with other OCC (breast cancer, prostate cancer, liver cancer and lung cancer)." (PMID 21364588, 2011).